EGFR (epidermal growth factor receptor)
Diseases named in the same sentence as EGFR in open-access papers (continued):
Sharing a sentence is not in itself a finding about the gene and the disease.
tumor (continued). "Though EGFR TKIs produce their most pronounced effects in patients with EGFR mutations, there is evidence that patients with wild-type EGFR also benefit from EGFR TKI treatment with significantly longer survival being observed with maintenance erlotinib in patients who had wild-type tumours." (PMID 22095222, 2011). "Cetuximab, an antibody targeting membrane EGFR, was shown efficient in improving the long-term survival of patients in association with radiotherapy and is approved as an active drug in H&N tumours." (PMID 22091418, 2011). "In our hospital, patients who couldn't provide sufficient tumor tissues preferred to choose body fluids for EGFR mutation analysis, but two problems were found in our practice when direct sequencing was used." (PMID 22142557, 2011). "Furthermore, the problem of EGFR overexpression loss has previously been overcome by direct implantation of tumor specimens into the flanks of nude mice." (PMID 21314332, 2011). "Indeed, it has been demonstrated that gain-of-function mutations in oncogenes such as HER2 or EGFR and loss-of-function mutations in tumor-suppressor genes such as VHL or PTEN induce HIF-1 activity." (PMID 21966417, 2011). "Also, inhibitors of EGFR kinase activity elicit cell death and tumor shrinkage in NSCLC patients with certain EGFR mutations." (PMID 21949687, 2011). "It is tempting to speculate that, since p.R776G has appeared as germ-line mutation, it would have a weaker effect on EGFR functions than the double mutations detected within the tumours." (PMID 21575252, 2011). "One possible reason may be the heterogeneous component of the cancers may have had an effect, so a random tumor section may have included wild-type EGFR cancer cells thereby missing the positive EGFR mutation component." (PMID 21858063, 2011). "We conclude that EBUS-TBNA of mediastinal lymph nodes infiltrated by NSCLC can provide sufficient tumour material for EGFR and KRAS mutation analysis in the great majority of patients without the need to resort to more invasive surgical mediastinoscopy or mediastinotomy." (PMID 21949883, 2011). "Although our results were obtained in a relatively small, single arm study, gefitinib-treated patients whose tumours contained low CEN7/cell (or low EGFR/CEN7 gain or low EGFR gain), high PTEN loss, and high PIK3CA gain had significantly shorter PFS and OS than other patients." (PMID 22095222, 2011). "As Ras activation is likely to promote tumor cell proliferation to assess whether successful inhibition of the EGFR signaling pathway is associated with KRAS mutations cell lines were examined for KRAS gene mutations." (PMID 20565817, 2010). "As TGF-α overproduction and consequent stimulation of the epidermal growth factor receptor (EGFR) is a hallmark of most RCC tumours, EGFR inhibitors (such as erlotinib and gefitinib) have a theoretical role in the treatment of RCC, on the basis of our understanding of the pathophysiology." (PMID 20823888, 2010). "The association between EGFR positivity and low-stage tumours is unusual." (PMID 20502457, 2010). "Both phospho-EGFR and EGFR overexpression were associated with tumour cell hyperproliferation; however, only EGFR was associated with adverse clinical outcome, thus suggesting that mechanisms other than EGFR activation may underlie its prognostic effect." (PMID 19997103, 2010). "Phospho-EGFR and EGFR expression were associated with tumour cell hyperproliferation." (PMID 19997103, 2010). "We therefore hypothesised that histological high-grade MECs, which have a clinically aggressive course, may harbour EGFR protein overexpression and high-EGFR gene copies linked to aggressive tumour biology." (PMID 20664595, 2010). "This suggests that the immunohistochemical analysis may be less sensitive than gene expression profiles to detect biologically relevant tumor characteristics linked to EGFR signaling." (PMID 20196851, 2010).
tumor (continued). "The activation of the EGFR/ERK pathway in these tumours is associated with aggressive behaviour and could represent potential indicators of response to EGFR antagonists or MAPK pathway inhibitors." (PMID 20664595, 2010). "Y-box binding protein-1 (YB-1) is a transcription and translation factor that alters the expression of at least ten genes strongly linked to drug resistance and tumour cell growth such as the epidermal growth factor receptor (EGFR) and the human epidermal growth factor receptor-2 (HER-2)." (PMID 20844753, 2010). "Since Stat3 inhibition also blocks VEGF expression in tumours characterized by aberrant activation of Src, therapeutic targeting of Stat3 may inhibit neovascularisation in tumours associated with excessive signaling through epidermal growth factor receptor." (PMID 20478049, 2010). "SH2 profiling therefore reveals heterogeneity of downstream signaling outputs despite common genomic properties (EGFR mutation), and could therefore provide additional predictive or prognostic information in tumor classification." (PMID 20976048, 2010). "As KRAS mutation status has been shown to be a predictor of tumor response to anti-EGFR treatment, the EVEREST trial sought to determine whether dose escalation would also be able to induce a response in patients with KRAS mutations." (PMID 20680104, 2010). "However, tumor response is mainly limited to patients who possess somatic mutations in the kinase domain of the EGFR gene." (PMID 24281220, 2010). "Moreover, the degree of EGFR over-expression is associated with an advanced tumour stage and resistance to standard therapies." (PMID 21176167, 2010). "Therefore, it would be important to evaluate the predictive value of such K-Ras mutated tumour subclones, particularly in stabilised or progressive cases treated by targeted EGFR therapy." (PMID 19293811, 2009). "It was suggested that the possible presence of such mutations at a low frequency in NSCLC tumours before EGFR-targeted therapy might affect the tumour response or the event-free survival after targeted treatments." (PMID 19293811, 2009). "We observed EGFR gene deregulation in 25 out of 36 primary tumours and 29 out of 36 metastases, K-Ras mutations in 16 out of 37 cancers and in 15 out of 37 metastases, BRAF mutations in 2 out of 36 cancers and 2 out of 36 metastases and PTEN loss in 8 out of 38 cancers and 12 out of 38 metastases." (PMID 19293803, 2009). "Studies of mouse embryonic fibroblasts (MEFs) from PS1-null mice and skin of adult PS1 conditional knockout mice, however, show that PS1 deficiency elicits tumor-like phenomena at least in part through stabilization of β-catenin and epidermal growth factor receptor (EGFR)." (PMID 19137062, 2009). "Recent findings have suggested that overexpression of EGFR is associated with tumour cell proliferation and survival, and this was attributed to maintaining the intracellular glucose level through interaction and stabilisation of the sodium/glucose cotransporter 1 (SGLT1)." (PMID 19888222, 2009). "Phosphorylation of EGFR tyrosine 845, only noticed in control tumors, is implicated in the stabilization of the activation loop, providing a binding surface for substrate proteins and is capable of regulating receptor function and tumor progression." (PMID 19878607, 2009). "An increase in EGFR copy number was also significantly associatedwith objective tumor response." (PMID 19365583, 2009). "Loss of androgen regulation of EGFR in PCa may be responsible for increased tumour growth, invasion, and metastasis, with important implications on the clinical management of PCa." (PMID 19888222, 2009). "Our previous findings that EGFR mutations were associated with tumor initiation while EGFR CNG might be more regarded as a tumor progression event, provide further evidence of their co-operative role in tumorgenesis." (PMID 19826477, 2009).
tumor (continued). "However, several retrospective studies on tumor biopsies and celllines found that EGFR gene mutations in CRC are extremely rare." (PMID 19365583, 2009). "Molecular characterisation of individual tumours, such as the association between EGFR (epidermal growth factor receptor) and radio-resistance is likely to play an important role in the near future to determine the aggressiveness of disease and the best outcomes from a variety of treatment options." (PMID 19442314, 2009). "Recently, expression of a tumour-specific constitutively active spliced variant of the receptor (EGFRvIII) was detected in 44% of a small cohort of HNSCCs and found to contribute to enhanced growth and resistance to wild-type EGFR-targeting antibodies." (PMID 18268492, 2008). "The objective of this study was to investigate the prevalence of EGFR and K-RAS mutations in metastases and to examine whether these mutations and the EGFR expression patterns are discordant between the primary tumours and the corresponding metastases." (PMID 19238633, 2008). "Therefore, EGFR mutation status showed a discordance of 28% (7 of 25 patients) (McNemar test, P=0.688) between the primary tumour and corresponding metastasis." (PMID 19238633, 2008). "We found that EGFR was significantly associated with high grade and high stage tumours." (PMID 19014499, 2008). "Multivariate analysis showed that EGFR expression was a significant prognostic factor (hazard ratio (HR), 2.67; 95% confidence interval (CI), 1.52–4.69; P=0.0006) and also a risk factor for tumour recurrence (HR, 1.89; 95% CI, 1.05–3.39, P=0.0335) in IHCC." (PMID 18087285, 2008). "Different somatic EGFR gene mutations may confer diverse tumor activation profiles that lead to variations in both natural history and clinical course after treatment with erlotinib or gefitinib." (PMID 19452042, 2008). "We hypothesised that EGFR-activating mutations in SGC might occur, making EGFR a potential molecular target for therapy also in these rare tumours with poor prognosis and limited response to traditional chemotherapies." (PMID 18542074, 2008). "Although it is unclear why EGFR expression in IHCC is an independent prognostic factor, it may be associated with frequent relapse of cancer because EGFR expression is also a risk factor for tumour recurrence." (PMID 18087285, 2008). "EGFR protein expression, as evaluated by immunohistochemistry, does not correlate with response and only specific treatment-induced skin rash seems associated with tumor response and progression-free survival." (PMID 18544172, 2008). "Furthermore, abrogation of EGFR signaling in tumor model systems blocks uPAR-associated invasiveness through an extracellular matrix and growth of tumors in animal models." (PMID 18519000, 2008). "Recently, an increasing body of experimental evidence has been provided to link tumor-specific molecular characteristics, such as epidermal growth factor receptor (EGFR) mutations and/or EGFR gene copy number with response to the EGFR inhibitors gefitinib and erlotinib in metastatic NSCLC." (PMID 19452042, 2008). "EGFR mutation status in the tumours and serum samples was consistent in 39 (92.9%) of the 42 pairs." (PMID 17848912, 2007). "However, these associations have only been marginally underscored using a multivariate regression model, except for the association between tumour phenotype and EGFR and/or ErbB2 overexpression." (PMID 17700572, 2007). "In addition, 1197 CRCs from TMA punches were randomised into two subgroups, the first used to select the cutoff scores for EGFR overexpression, the second to analyse EGFR overexpression and its association with tumour progression and survival." (PMID 17311026, 2007). "EGFR expression was significantly associated with response to cisplatin-based chemotherapy: the response rates were 50 and 22% in patients with EGFR-positive tumours and EGFR-negative tumours, respectively (P<0.05)." (PMID 17876336, 2007).
tumor (continued). "Since the previous study did not clarify the feasibility of using serum DNA as a practical source for detection of EGFR mutations, in the present study, we sought to demonstrate that EGFR mutation status determined in serum DNA is the same as in actual tumour samples." (PMID 17848912, 2007). "The progression of this tumor is associated with multiple genetic alterations, including loss of heterozygosity in chromosomes 3p, 5q, 9p, 9q, 13q, 17p, 17q and 18q, and amplification of epidermal growth factor receptor (EGFR), HER-2, c-myc, and cyclin D1." (PMID 17309796, 2007). "The reasons for targeting EGFR in anticancer therapy are: the importance of EGFR signalling in the development of tumours; the association between EGFR overexpression and poor prognosis in many cancers; and the distinct mechanism of action of anti-EGFR approaches versus conventional methods." (PMID 21614219, 2006). "Because mutational status of EGFR has been shown in select studies to correlate with tumor response to erlotinib and gefitinib, we chose to further validate our model on a series of resected adenocarcinomas for which mutational status, as well as pEGFR status was known." (PMID 17096850, 2006). "Since persistently activated EGFR (pEGFR) may reflect underlying tumor reliance on EGFR and therefore sensitivity to EGFR TKI, we explored the relationship between classification by DLDA and pEGFR staining." (PMID 17096850, 2006). "Low level of EGFR expression in germline tumour cells may be linked to their drug sensitivity and supports a positive role for EGFR in drug resistance of cancer." (PMID 15655552, 2005). "This may be particularly relevant in tumours with a dependency upon EGFR signalling, for example in certain tumours harbouring activating mutations in EGFR." (PMID 15928657, 2005). "Moreover, TNF-α is one of the angiogenic factors associated with tumour-induced neovascularisation and gefitinib has been shown to inhibit EGFR-mediated migration and tube-like formation of human microvascular endothelial cells." (PMID 15841081, 2005). "In this study cohort, 13 patients (7 HER3− and 6 HER3+) had tumours with EGFR gene mutations." (PMID 16288303, 2005). "Although initial studies suggested that only tumours harbouring EGFR mutations would be sensitive to EGFR tyrosine kinase inhibitors, there are compelling data to suggest that tumours harbouring EGFR amplification may also respond well to these new agents." (PMID 16280056, 2005). "The concordance for commonly known activating EGFR mutations was 88 %, indicating better performance for specific clinically relevant mutations, and strongly suggests that cfDNA can assist in treatment decisions of majority cases, where at times the tumor tissue cannot be obtained." (PMID 40503459, 2025). "EGFR is believed to be activated to p-EGFR, and it may be associated with tumor staging or grading." (PMID 40738059, 2025). "Importantly, tumor cells from patients with EGFR mutation showed increased expression of several MHC class I and II genes compared to tumor cells from patients with KRAS mutant tumors, along with an increase in CD74, which regulates the presentation of MHC class II proteins." (PMID 39803458, 2025). "However, whether EGFR mutations directly influence IL-35 production in the tumor microenvironment remains unexplored." (PMID 41357575, 2025). "In addition to amplifying specificity to EGFR-positive tumors, dual targeting of both EGFR and PD-L1 by a bispecific Nanofitin could address the on-target/off-tumor effects associated with PD-L1 monospecific targeting." (PMID 40305184, 2025). "Therefore, tumors harboring acquired T790M mutation, acquired EGFR amplification, and EGFR‐sensitive mutations may synergistically amplify the reliance of tumor cells on the EGFR pathway at a molecular level." (PMID 39741120, 2025).
tumor (continued). "Another pathological analysis of NSCLC patients carrying EGFR mutations revealed that MUC5B expression levels in tumor tissues were strongly associated with patient overall survival, indicating that MUC5B may act as a novel prognostic biomarker in this subgroup." (PMID 41011152, 2025). "Notably, EGFR mutation status correlated positively with increased infiltration of these immunosuppressive cells and, consequently, with elevated IL-35 expression in tumor tissues." (PMID 41357575, 2025). "On the other hand, tumors with point mutations like KRAS or EGFR may follow a branched evolution, developing multiple subclones in parallel, each acquiring diverse passenger or even additional driver mutations over the course of tumor development." (PMID 40723270, 2025). "Moreover, the EGFRvIII mutation frequently coexists with EGFR amplification, and the coexistence of these two malignant alterations may indicate tumor progression and increased treatment challenges." (PMID 40331985, 2025). "Tumor-associated macrophages, through the secretion of pro-inflammatory factors, may amplify EGFR activation within the tumor microenvironment, rendering tumor cells resistant to EGFR-TKI therapy." (PMID 40003951, 2025). "A study conducted on erlotinib-resistant rodent models (having the human EGFR T790M erlotinib-resistance mutation) showed that several transcriptome changes occur that allow for metabolic adaptation, upregulation of oxidative stress defense mechanisms, and tumor progression pathways." (PMID 40862737, 2025). "However, osimertinib has demonstrated high efficacy in NSCLC patients harboring the T790M resistance mutation detected through ctDNA, even in cases where tumor mutation status is unknown and progression has occurred following prior EGFR-TKI therapy." (PMID 41373464, 2025). "These mutations increase EGFR amplification and interleukin 6 (IL-6) levels, inducing angiogenesis and tumor necrosis, and decrease glycogen accumulation, limiting glucose oxidation, nucleic acid and de novo fatty acid synthesis, and promoting tumor cell apoptosis." (PMID 41007844, 2025). "We hypothesize that the effectiveness of these drugs may depend on the activated oncogene abundance when the tumor is driven by two distinct driver genes, detecting the abundance of EGFR mutations and BRAF mutations is crucial for optimizing the selection of TKIs in clinical practice." (PMID 40242250, 2025). "Notably, variations in smoking history, EGFR mutation status, tumor histopathology, and treatment regimens may influence the observed microbial profiles." (PMID 41471248, 2025). "Consequently, mutations in EGFR or Src across different cellular contexts may differentially redirect TNS3’s functional impact on tumor progression." (PMID 40906372, 2025). "Furthermore, numerous studies have demonstrated high concordance between ctDNA and tissue‐based EGFR mutation testing, including for T790M; however, discordance may occur due to tumor heterogeneity, variations in ctDNA shedding, or technical limitations." (PMID 41221800, 2025). "While our patient presented with EGFR-mutant circulating tumor cells (CTCs) and showed a favorable response to EGFR TKIs, we were unable to validate this finding with molecular-based EGFR mutation profiling (e.g., polymerase chain reaction or next-generation sequencing) of the tumor biopsy." (PMID 41040516, 2025). "This cutting-edge technology allows for an in-depth exploration of tumor cell complexity and heterogeneity, shedding light on the diverse gene expression patterns linked to resistance and enhancing our understanding of how the tumor microenvironment contributes to EGFR-TKI resistance." (PMID 40003951, 2025).